FKBP5 (FKBP prolyl isomerase 5)
Diseases named in the same sentence as FKBP5 in open-access papers (continued):
Sharing a sentence is not in itself a finding about the gene and the disease.
melanoma (13 papers, 2011 to 2025). A malignant, usually aggressive tumor composed of atypical, neoplastic melanocytes. "The spliced isoform 2 of the FKBP5 gene, FKBP51s, was first identified in melanoma patients; it is codified by the transcript variant 4 (NM_001145777.1 mRNA)." (PMID 37415743, 2023). "Our research has previously identified a role for a spliced variant of the FKBP5 gene in the regulation of PD-L1 expression in melanoma." (PMID 28978117, 2017). "FKBP5 modulates immune response via PD-L1 and promotes stemness and metastatic potential in melanoma." (PMID 40954493, 2025). "In malignant melanoma, it has been reported that FKBP5 took part in the apoptosis resistance and promoted autophagy response to ionizing radiation." (PMID 37452039, 2023). "In malignant melanoma subjected to ionizing radiation, FKBP5 was related to apoptosis resistance while inducing autophagy." (PMID 32760250, 2020). "On the other hand, FKBP5 has also been shown to be downregulated in pancreatic cancer, melanoma, colon cancer, and testicular cancer." (PMID 21119664, 2011). "For example, FKBP5 is found to be downregulated in pancreatic tumour tissue, while it is overexpressed in melanoma." (PMID 21119664, 2011). "Particularly, FKBP5 played an essential role in the resistance of melanoma to radiotherapy." (PMID 36769373, 2023). "It has been reported that FKBP5 can promote autophagy and increase the radioresistance of melanoma." (PMID 36769373, 2023). "Interestingly, it has been shown that Fkbp5, a key molecule in melanoma growth, regulates IL-8 production." (PMID 37882535, 2023). "These experiments provided evidence that, both in vitro and in vivo, FKBP5 might be a promising target for radiosensitising agents against malignant melanoma." (PMID 21119664, 2011). "In addition, the same group also found that higher expression of FKBP5 might influence radioresistance through the activation of NF-κB in melanoma cells." (PMID 21119664, 2011).
breast carcinoma (12 papers, 2011 to 2025). "We profiled the expression of selected stress-associated genes (5-HTT, NR3C1, OXTR, and FKBP5) in breast cancer including the stress evaluation of all participants using the Questionnaire on Distress in Cancer Patients–short form (QSC-R10)." (PMID 36430579, 2022). "This family of genes plays an inhibitory role in tumour progression, including the inhibitory effect of FKBP5 on breast cancer and the antiapoptotic effect of FKBP51 in melanoma." (PMID 38321105, 2024). "Changes in FKBP5 gene expression were found in gastric cancer, pancreatic cancer, breast cancer, and papillary thyroid carcinoma." (PMID 36531220, 2022). "Survival curves showed that patients with high mRNA levels of FKBP5 have high overall and distant-free metastatic survival probability, indicating a positive prognosis in breast cancer morbidity." (PMID 36430579, 2022). "In breast cancer, FKBP5 is the most extensively studied protein among identified human FKBPs, which is demonstrated to interact with HSP90 to affect steroid hormone receptor function." (PMID 32194784, 2020). "FKBP5 is down-regulated in breast cancer, and its abundance in cancer cells renders them sensitive or resistant to gemcitabine and AraC." (PMID 21811619, 2011). "This means that downregulation of FKBP5 may also lead to tumors, which has been reported in pancreatic cancer and breast cancer." (PMID 34895219, 2021). "Furthermore, downregulation of FKBP5 desensitised pancreatic and breast cancer cell lines to several different classes of chemotherapeutic agents, including not only cytidine analogues but also taxanes, ironotecan, and etoposide." (PMID 21119664, 2011). "We also observed downregulation of FKBP5 in breast cancer cell lines." (PMID 21119664, 2011).
diabetes (12 papers, 2011 to 2025). "Diabetes itself was associated with increased FKBP5 methylation at both sites, particularly in individuals without regular exercise." (PMID 40017583, 2025). "Increased methylation of cg00862770 is linked to reduced FKBP5 expression, impaired glucose uptake, and exacerbation of diabetes-related metabolic dysfunction." (PMID 40017583, 2025). "In contrast, HFD beta cells showed reduced expression of genes associated with beta cell function (i.e., Fos, Fosb, Jun, and the incretin receptor Gipr), and increased expression of stress- and diabetes-associated genes (Fkbp5 and Glis3, respectively)." (PMID 39433757, 2024). "In individuals with diabetes, FKBP5 methylation is associated with an increased incidence of clinical risk factors for disease." (PMID 38786025, 2024). "More recently, human genetic studies also reported associations of the FKBP5 hyper-inducing alleles with diabetes and trauma-related chronic pain." (PMID 30669684, 2019). "Additionally, the cross-sectional design limits causal inferences about the relationship between exercise, diabetes, and FKBP5 methylation." (PMID 40017583, 2025). "DEGs involved in hydrolysis of carbohydrate may provide insights into the previous association of Fkbp5 with diabetes." (PMID 38201293, 2023). "In conclusion, this study highlights the interplay between exercise, diabetes, and FKBP5 methylation at key CpG sites." (PMID 40017583, 2025). "This stratified analysis highlighted the potential interactions among diabetes, exercise, and FKBP5 methylation, considering the metabolic and inflammatory changes associated with diabetes." (PMID 40017583, 2025). "Recent studies have begun to explore a possible connection between methylation of the FKBP5 gene and diabetes." (PMID 40017583, 2025). "This study investigates the interaction between exercise, diabetes, and FKBP5 methylation at cg22363520 and cg00862770 and explores their implications for mental health and disease development." (PMID 40017583, 2025). "Multiple linear regression models assessed the main effects and interactions of exercise and diabetes on FKBP5 methylation, with further stratified analyses for site-specific effects." (PMID 40017583, 2025). "Materials and Methods: FKBP5 methylation levels at cg22363520 and cg00862770 were analyzed in a cohort stratified by diabetes and exercise." (PMID 40017583, 2025). "This study focuses on two key CpG sites, cg22363520 and cg00862770, due to their regulatory roles in FKBP5 expression and stress response and their relevance to the metabolic disease diabetes." (PMID 40017583, 2025). "Therefore, the purpose of this article is to explore the potential relationship between exercise, diabetes, and methylation of the FKBP5 gene." (PMID 40017583, 2025). "Recent research also suggests that methylation of the FKBP5 gene may be related to mental health, stress response, and diabetes." (PMID 40017583, 2025). "Our results suggest that diabetes modifies the relationship between exercise and FKBP5 methylation." (PMID 40017583, 2025). "The cg22363520 and cg00862770 loci within the FKBP5 gene could serve as biomarkers for evaluating the effectiveness of exercise interventions in diabetes management." (PMID 40017583, 2025). "The effects of diabetes and exercise on FKBP5 gene methylation observed in this study may further support psychological health interventions." (PMID 40017583, 2025). "However, more research is still needed to fully understand whether exercise and diabetes have regulatory effects and effects on DNA methylation of the FKBP5 gene." (PMID 40017583, 2025). "Additionally, significant interaction effects between exercise and diabetes were identified for both cg22363520 (p = 0.0336) and cg00862770 (p = 0.0021), highlighting the interplay between metabolic status and physical activity in regulating FKBP5 methylation." (PMID 40017583, 2025).
diabetes (continued). "Because of the role of FKBP5 in the regulation of multiple important biological pathways as discussed in this review, variation in FKBP5 could be of significance in many diseases beyond cancer, and in diseases such as diabetes." (PMID 21119664, 2011). "Changes in GR signaling were compounded by increased expression of GR, and reduced expression of FKBP5 and HSD11B2 in diabetes." (PMID 36068241, 2022). "Our research results indicate that participants who exercise and have diabetes are more likely to have methylation at the cg22363520 locus of the FKBP5 gene compared to those who exercise but do not have diabetes, and this gene is less likely to be expressed." (PMID 40017583, 2025).
bipolar disorder (11 papers, 2006 to 2025). A disorder of the brain that causes unusual shifts in mood, energy, activity levels and the ability to carry out day-to-day tasks. "Another bipolar disorder study genotyped eight common FKBP5 variants and found that a haplotype block containing seven of the variants was associated with attempted suicide." (PMID 28030643, 2016). "A family-based study found an association with FKBP5 and bipolar disorder, and a secondary analysis linked this to a history of attempted suicide." (PMID 28030643, 2016). "The goal of this study was to investigate whether variants within the FKBP5 region, separately or together, influence suicidal behavior in individuals with bipolar disorder." (PMID 28030643, 2016). "Therefore, in this study, we have sequenced both coding regions and regulatory regions to identify genetic variation in FKBP5 that may increase the risk for suicidal behavior in individuals with bipolar disorder." (PMID 28030643, 2016). "In a sample of patients with unipolar and bipolar depression, it was concluded that in TT homozygotes, both GR signaling and HPA axis reactivity were more controlled by the interaction between FKBP5 and the GR than in carriers of the CT or CC genotypes." (PMID 40149476, 2025). "We developed a systematic, targeted sequencing approach to investigate coding and regulatory regions in or near FKBP5 in 476 bipolar disorder suicide attempters and 473 bipolar disorder non-attempters." (PMID 28030643, 2016).
Cushing syndrome (11 papers, 2017 to 2025). Cushing's syndrome (CS) encompasses a group of hormonal disorders caused by prolonged and high exposure levels to glucocorticoids that can be of either endogenous (adrenal cortex production) or exogenous (iatrogenic) origin. "It has already been shown that overexpression of FKBP5 RNA levels is associated with Cushing’s syndrome." (PMID 40130164, 2025). "In humans, genetic variants and hypomethylation within intron 2 of FKBP5 have been associated with Cushing’s syndrome." (PMID 32958048, 2020). "In patients with Cushing’s syndrome there was a positive association between FKBP5 methylation in blood and bilateral hippocampal volume." (PMID 32151655, 2020). "Epigenetic modification via loss of intronic methylation of FKBP5 has been associated with Cushing’s syndrome and can serve as an indicator of chronic exposure to cortisol." (PMID 29951131, 2018). "Although the expression levels of FKBP4 and FKBP5 in corticotroph tumors have not been determined, reduced leukocyte DNA methylation of FKBP5 and increased FKBP5 mRNA levels in blood have been found in patients with Cushing’s syndrome." (PMID 36672445, 2023). "Excessive exposure to cortisol in patients with Cushing syndrome induces high FKBP5 mRNA expression in blood cells, which returned to baseline after successful surgery." (PMID 37492570, 2023). "This FKBP5 promoter region included 5 CpG sites, whose methylation level properly discriminated overt Cushing’s syndrome samples from all the others (t-test P -value < 0.05)." (PMID 34914631, 2022). "In Cushing’s syndrome, an enrichment in hypomethylated CpG sites was observed in the region of FKBP5 gene locus." (PMID 34914631, 2022). "One study demonstrated that a decrease in methylation of an intron 2 site of FKBP5 is present in Cushing’s syndrome." (PMID 29951131, 2018). "However, in patients with Cushing syndrome, it has been shown that long standing excessive endogenous hypercortisolism induces hypomethylation in FKBP5, explaining their long-lasting psychopathological sequelae." (PMID 38395991, 2024). "Furthermore, a recent study showed a correlation between FKBP5 expression and cortisol levels in patients with Cushing’s syndrome." (PMID 34914631, 2022). "Since promoter methylation usually negatively correlates with gene expression, we measured FKBP5 gene expression in a subset of 37 samples (14 overt Cushing’s syndrome, 10 mild Cushing’s syndrome, 7 eucortisolism, 6 adrenal insufficiency), for which whole blood RNA was available." (PMID 34914631, 2022). "Particularly, one single CpG site from the FKBP5 gene locus could discriminate overt Cushing’s syndrome samples." (PMID 34914631, 2022). "In addition, FKBP5, a gene that was recently found to be differentially methylated in Cushing’s syndrome, was not among the genes identified in our study." (PMID 28231836, 2017).
type 2 diabetes (11 papers, 2017 to 2025). "FKBP5 expression in human subcutaneous adipose tissue tends to be increased in type II diabetes subjects and is associated with genes involved in lipid metabolism and adipogenesis." (PMID 36397714, 2023). "FKBP5 methylation has been associated with type 2 diabetes and cardiovascular risk and FKBP5 polymorphisms are associated with insulin resistance." (PMID 36068241, 2022). "Aberrant DNA methylation at FKBP5 cytosine–phosphate–guanine (CpG) sites, such as cg22363520 and cg00862770, has been implicated in mental health disorders and metabolic diseases, including Type 2 diabetes." (PMID 40017583, 2025). "Also, variants in the FKBP5 gene were shown to be associated with type 2 diabetes and diabetes-related phenotypes." (PMID 32601291, 2020). "In this context, it is possible that stress-induced FKBP5 may similarly be implicated in additional stress-related pathophysiologies, such as type 2 diabetes (T2D)." (PMID 29170369, 2017). "SNPs in FKBP5 are associated with type 2 diabetes mellitus (T2D), body weight change and insulin resistance." (PMID 37726498, 2024).
hypercortisolemia (10 papers, 2018 to 2026). "Of particular relevance, in vitro dexamethasone treatment has been found to induce an active demethylation of FKBP5 intron 7 in human hippocampal progenitor cell lines, which may impose an increased risk for a chronic state of hypercortisolism." (PMID 35173143, 2022). "In the case of FKBP5, studies show different genotypes have various levels of susceptibility to environmental stress and transcription of the gene, thereby contributing to hypercortisolemia and glucocorticoid resistance." (PMID 30619472, 2018). "FKBP5 mRNA expression returns to normal baseline values upon successful surgical resolution of the hypercortisolism." (PMID 34258233, 2021). "The FKBP5-mediated impairment of GR nuclear translocation in both central and peripheral tissues fosters glucocorticoid resistance, perpetuating hypercortisolemia and a pro-inflammatory milieu that directly accelerates osteoblast apoptosis and bone deterioration." (PMID 41683869, 2026). "Cluster 2 exhibited elevated basal corticosterone, a blunted dexamethasone response, anhedonia, and reduced immobility in the forced swim test; increased Crh and reduced Fkbp5 suggested enhanced glucocorticoid receptor sensitivity and sustained hypercortisolemia." (PMID 41373593, 2025). "Next, we investigated whether FKBP5 DNAM would be associated with an acute (i.e., cortisol stress response to the TSST) and chronic (i.e., HCC) state of hypercortisolism." (PMID 32488091, 2020). "Molecularly, elevated Crh promotes HPA axis hyperactivation, while reduced Fkbp5 may enhance glucocorticoid receptor sensitivity, leading to prolonged transcriptional effects of corticosterone and likely contributing to the observed hypercortisolemia." (PMID 41373593, 2025). "Interestingly, increased methylation of SNPs in the FKBP5 gene (e.g., rs9296158) and some CRHR1 gene polymorphisms that produce high levels of CRH are associated with cortisol hypersensitivity and hypercortisolism and represent a distinct PTSD phenotype from that characterized by hypercortisolism." (PMID 37374323, 2023). "One of the target genes is FKBP5, and its transcriptional activation by the GR dimer creates a negative feedback loop, whereby hypercortisolemia and glucocorticoid resistance can be attributed to the excess FKBP5 protein that has enhanced affinity for the glucocorticoid receptor." (PMID 30619472, 2018).
mood disorder (10 papers, 2013 to 2024). A cognitive disorder a disturbance in which the person's mood is hypothesized to be the main underlying feature. "Specifically, the study identified child abuse as a risk factor for mood disorders and demonstrated a connection to reduced DNA methylation of FKBP5 intron 7, particularly through interactions with the SNP rs1360780." (PMID 38786025, 2024). "FK-506 binding protein 5 (FKBP5) codes for the protein Fkbp51, a heat shock protein 90 kDa (Hsp90) co-chaperone, which is associated with several mood disorders." (PMID 37189827, 2023). "Together, these findings indicate that variations in FKBP5 are associated with mood disorders and suicidal behaviors." (PMID 36781843, 2023). "It is known that the genetic polymorphism of the gene Nr3c1 GR and the protein regulating GR, the so-called FK506-binding protein 51 (Fkbp5 gene), is associated with the pathophysiology of mood disorders in the human population." (PMID 30814974, 2019). "Unfortunately, research on the neuroendocrine system-related candidate gene FKBP5 in mood disorders is currently highly limited, highlighting the need for further studies in this area." (PMID 38609904, 2024). "Specifically, genes, such as NR3C1, SLC6A4, BDNF, FKBP5, SKA2, and OXTR, exhibit alterations in DNA methylation patterns that are frequently linked to mood disorders." (PMID 38792892, 2024). "Four of our 16 candidate proteins have previously been investigated in relation to mood disorders or suicide (FKBP5, FGFR2, SCGB1A1, and CD63), but most candidate proteins are novel to mood disorders and suicide research." (PMID 35697758, 2022). "Despite the extensive literature about the role of the hippocampus in mood disorders, there are limited studies examining the role of FKBP5 and stress affecting AKT in hippocampal axes." (PMID 31167373, 2019). "Our findings highlight the importance of stress and genes (like FKBP5) in modulating vulnerability to mood disorders and learning impairments." (PMID 31167373, 2019). "Moreover the level of BDNF with SLC64 is utilized as a biomarker to diagnose mood disorders in diseased/healthy subjects, and there are many other genes (NR3C1 and FKBP5) that have also been linked to the early diagnosis of mood disorders." (PMID 36766442, 2023). "Among these were FKBP5 and WFS1, which have been previously implicated in mood disorders." (PMID 23945090, 2013).